TNF (tumor necrosis factor)
Diseases named in the same sentence as TNF in open-access papers (continued):
Sharing a sentence is not in itself a finding about the gene and the disease.
colitis (continued). "As a result, they demonstrated increased expression of Entpd1 and elevated cAMP levels also influenced platelet aggregation and TNFα production, linking the findings observed in a pre-clinical model of colitis back to human IBD." (PMID 38179052, 2023). "Macrophages produce TNF-α in large quantities in response to pro-inflammatory processes, and cytokine performs various functions in the development of colitis." (PMID 37427322, 2023). "Oral gavage of Rd or CK at doses of 1 mg/kg and 5 mg/kg also suppressed IS-induced colitis: their treatments alleviated colon shortening and down-regulated colonic myeloperoxidase, TNF-α, and IL-6 expression, and NF-κB+CD11c+ cell number." (PMID 36926604, 2023). "Accumulating evidence suggests that EUP inhibits excessive production of pro-inflammatory cytokines such as tumor necrosis factor-α (TNF-α) in animal models of gastric mucosal injury, inflammatory skin diseases, asthma, anaphylactic shock, and colitis." (PMID 37754228, 2023). "Ruminococcus-gnavus secretes glucorhamnan, a complex polysaccharide with a rhamnose skeleton and glucose side chain, which induces dendritic cells to secrete inflammatory cytokines (TNF-α), thus leading to colitis development." (PMID 37580334, 2023). "L-theanine also weakly decreased the expression of IL-1β, IL-6, and TNF-α, which are neuroinflammation- and colitis-related biomarkers." (PMID 37299451, 2023). "Inflammatory cytokines including IL-1β, TNF-α, and IL-6 are linked with effects of the fecal microbiome on ICI colitis; IL-6 also drives irAEs in other organs." (PMID 36622383, 2023). "Accordingly, we found that integrin β6 deficiency remarkably decreased the release of pro-inflammatory cytokines including TNF-α, IL-6 and IL-1β in the intestinal tissues of colitis." (PMID 37223685, 2023). "The inflammatory cytokines including TNF-α, IL-1β, IL-6, and IL-10 were higher in colitis mice than those in control mice (P < 0.01)." (PMID 36768559, 2023). "The balance between pro-inflammatory cytokines, including IL-6, IL-1β, and TNF-α, usually plays a crucial pathological role in colitis by mediating inflammatory responses." (PMID 38138587, 2023). "In this study, high concentrations of colonic TNF-α, IL-6, and IL-1β were observed in mice with colitis, which was in agreement with a previous study." (PMID 37762155, 2023). "As another common side effect of ICB, colitis is commonly treated with immunosuppressive drugs, including corticosteroids and/or agents targeting tumor-necrosis factor-α (TNF-α), all of such have obvious side effects." (PMID 36969071, 2023). "Administration of WY14643 significantly ameliorated colitis symptoms and reduced the expression levels of inflammatory genes, such as interferon-γ, tumor necrosis factor-α, interleukin-1β, and interleukin-6 in colon tissues." (PMID 36614242, 2023). "To determine the mechanism by which neutrophils contribute to colitis, we examined the production of inflammatory factors including TNF-α, IL-1β, and IL-6." (PMID 37813835, 2023). "Supplementation with dihydroquercetin significantly reversed DSS-induced colitis in mice via down-regulating levels of IL-1β, IL-6, TNF-α, and up-regulating serum IL-10, colonic ZO-1, occludin, and Lactobacillus levels." (PMID 37298531, 2023). "IL23 blockade reduced the number of IFNγ producing CD4+ T cells in the colon in CPI colitis and especially IFNγ/TNFα co-producing cells." (PMID 37872166, 2023). "Ligliptin activated the AMPK-SIRT1-PGC-1α pathway and inhibited the JAK2/STAT3 signaling pathway, downregulated TNF-α, IL-6 and NF-κB p65, and upregulated the anti-inflammatory cytokine IL-10, reducing the severity of colitis." (PMID 37483618, 2023). "In our study, IL-1β, TNF-α, IL-6, and IL-17A contents within the colon increased after CR infection, conforming to prior research regarding CR-induced colitis." (PMID 37111225, 2023).
colitis (continued). "Excess TNF-α has been reported to enhance local or systemic inflammation, disrupt tight junctions, leading to worsening colitis." (PMID 37631047, 2023). "In coptisine chloride therapy for colitis, coptisine chloride significant suppresses mRNA expression, releases of pro-inflammatory cytokines (TNF-α, IFN-γ, IL-1β, IL-6, IL-17) and enhances the mRNA expression level of IL-10, an anti-inflammatory cytokine." (PMID 36859380, 2023). "In line with DSS colitis model results, the secretion of TNF-α, IL-1β, and IL-6, were also obviously reduced in response to LPS when administered with phenolic acids." (PMID 37813835, 2023). "The attenuation of TNF-α levels and colitis symptoms was also found in an experiment with wild-type and adiponectin knockout mice following 4 weeks of exercise training." (PMID 36814502, 2023). "L. casei LC2W improved symptoms of colitis induced with E. coli O157:H7 by protecting tight junctions and reducing IL-1β, TNF-α and IL-6 in the colon." (PMID 36986118, 2023). "Because inflammatory cytokines play an important role in the response to colitis, we detected the expression levels of proinflammatory cytokines TNF-α and IFN-γ in the serum by ELISA." (PMID 37727787, 2023). "EVs from broccoli proved to improve colitis by reducing the expression of TNF-α, IL-17, and IFN-γ while decreasing IL-10." (PMID 38201294, 2023). "PA/CCMTS-P showed excellent anti-inflammatory effects both in vitro and in vivo, which obviously reduced the secretion of TNF-α, IL-6, IL-1β, and IL-18 after LPS stimulation in Raw264.7 cells, and the expression of IL-1β and IL-18 at the colitis site in vivo." (PMID 36843930, 2023). "Esculetin has been demonstrated to ameliorate TNBS-induced rat colitis, and attenuate the expression of pro-inflammatory mediators TNF-α and IL-1β." (PMID 37161415, 2023). "NETs can activate macrophages to release cytokines such as IL-1β, TNF-α, IL-6, induce the activation of platelets and intestinal epithelial cells, promoting colitis and thrombosis." (PMID 37720208, 2023). "TNF-α is considered the key molecule, shown by the fact that when mice with TNBS-induced colitis were treated by intraperitoneal injection of antibodies to TNF-α, improvements of both the clinical and histopathological signs of disease were found." (PMID 37569412, 2023). "Proinflammatory cytokines play a critical role in DSS-induced colitis injury as significant elevation of TNF-α, IL-1β, and IL-6, at both mRNA and protein levels, was observed by QRT-PCR and ELISA." (PMID 37284442, 2023). "The activation of LXRs in a mouse colitis model can suppress the expression of inflammatory factors such as IL-1β, IL-6, IL-17A, TNFα, and chemokines such as CXCL1/KC, CXCL2/MIP2, CXCL8/IL-8, CCL2/MCP1 and CXCL10 in the colon tissue." (PMID 37720208, 2023). "Previous studies have demonstrated that the derangement of cytokines drives colitis pathology and disease progression, TNF‐α, IL‐1β, and IL‐6 are important pro‐inflammatory effectors that function in the context of intestinal inflammation." (PMID 37970386, 2023). "Since circulating TNFα levels were elevated during DSS colitis (Fig EV1D), we investigated its effects on adipocyte lipid metabolism." (PMID 36795015, 2023). "Esculin was found to significantly alleviate the symptoms of colitis and suppress the expression of inflammatory factors including inducible nitric oxide synthase (iNOS), tumor necrosis factor-α (TNF-α), and interleukin-1β (IL-1β) in vivo and in vitro." (PMID 37800835, 2023). "The available clinical data suggest that anti-IL-6 and anti-TNF-α monoclonal antibodies have a certain ameliorative effect on patients with colitis." (PMID 37595257, 2023). "Quercetin can inhibit pro-inflammatory factor generation, such as IL-17, TNF-α, or IL-6, while promoting IL-10 production during CR-induced colitis." (PMID 37111225, 2023).
colitis (continued). "In the inflammatory response, inhibition of TNF-α expression in serum can reduce colitis, and these changes also indicate that TNF-α plays an important role in the development of colitis to colon tumors." (PMID 36713833, 2023). "As previously reported, the mRNA levels of inflammatory cytokines, Il6 (the gene encoding interleukin 6 (IL-6), Il17a, Tnf (the gene encoding tumor necrosis factor α), and Il1b, were increased in the colon of Vdr(+/−) mice with DSS-induced colitis." (PMID 36834927, 2023). "Viable cells of L. paracasei strain MSMC39-1 were used in colitis rat models due to their strongest suppression effect on TNF-α production in LPS-stimulated Caco-2 cells." (PMID 36986118, 2023). "Deletion of optineurin leads to mistransportation of cytokines such as TNF and IL6 to lysosomes, thereby reducing serum TNF levels and making mice more susceptible to Citrobacter rodentium-induced colitis." (PMID 37152076, 2023). "MSC-CM administered intraperitoneally has demonstrated to improve the symptoms of experimental colitis and decrease TNF-α and MMP2 expression in mice." (PMID 36012170, 2022). "We next investigated the effects of rapamycin on p65 expression and TNF-α production in both TNBS-induced colitis and LPS-stimulated HT-29 cells." (PMID 36032781, 2022). "Mechanistically, overexpression of PFKFB3 induced phospho-p65 and promoted the expression of IL-1β and TNF-α in the development of colitis and CAC." (PMID 36016583, 2022). "The cytokine levels (IL-6, IFN-γ, and TNF-α) in the colitis mouse colon on Day 14 were much higher than those in healthy mice." (PMID 35893896, 2022). "AX and L. fermentum HFY06 inhibited the activation of the NF-κB signaling pathway, downregulated the mRNA expression levels of NF-kBp65 and inhibited the TNF-α, and exerted anti-colitis effects." (PMID 35990343, 2022). "Oral roflumilast dose-dependently improved the clinical score of colitis, reduced the colonic shortening, and decreased local TNFα expression in colonic tissue; however, this improvement was not correlated with a decreased histological score." (PMID 35239781, 2022). "In another study, mice with TNBS-induced colitis showed heightened behavioural despair and increased hippocampal TNF-α, inducible nitric oxide synthase (iNOS), and nitrite expression." (PMID 34983592, 2022). "Naringin supplementation reduced the development of colitis induced by DSS in mice through suppression of epithelial TNF-α production." (PMID 35805952, 2022). "Alleviated the severity of the disease in a colitis mouse model by decreasing mRNA expression of TNF- α and iNOS." (PMID 35208860, 2022). "In the DSS-colitis mice, supplementation of CPn or citrus residues (from juice extraction) decreased the expression of pro-inflammatory genes (TNF-α, IL-1β/-16, iNOS, ICAM-1) and colon weight/length ratio." (PMID 35399093, 2022). "Significant increase was observed in the level of TNF-α in colitis group that was decreased after the treatment of MSCs." (PMID 36228298, 2022). "Macrophages in the colon will trigger and exacerbate DSS-induced colitis by releasing cytokines, such as IL-6, TNF-α, and IL-1β." (PMID 36189321, 2022). "It was suggested that inhibition of these cytokines and inflammatory mediators (NO) production by blocking TNF-α signaling led to suppression of inflammatory cell infiltration, leading to attenuation of colitis." (PMID 35939430, 2022). "Overactivity of pro-inflammatory factors such as IL-1β, IL-6, and TNF-α play important roles in inducing and maintaining colitis intestinal inflammation." (PMID 35645824, 2022). "Selective deletion of IL-1β or neutralization of TNF-α in Ly6Chi monocytes suppresses colitis in mice." (PMID 34912006, 2022). "TNFα mRNA level increased with the inflammation onset and reached its peak on day 7, with values returning to normal during the resolution of colitis in both strains." (PMID 35628317, 2022).
colitis (continued). "Similar to ALG, B. animalis and HDCA exerted a strong anti-inflammatory effect in DSS-induced colitis by downregulating inflammatory cytokines (interleukin-1β [IL-1β], IL-6, and tumor necrosis factor alpha [TNF-α])." (PMID 36219101, 2022). "In particular, the expression of the pro-inflammatory cytokines TNF-α and IL-6 correlates positively with the severity of colitis." (PMID 36159466, 2022). "Colitis is characterized by abnormal levels of inflammatory cytokines, especially TNF-α, IL-6, and IL-1β." (PMID 35681301, 2022). "Sinapic acid reduces diarrhea in colitis-induced murine models, reducing TNF-α and myeloperoxidase production." (PMID 35056616, 2022). "In sum, we conclude that TNF produced by T cells during colitis acts as membrane-bound molecule to promote inflammation." (PMID 35383266, 2022). "The results showed that colitis induction resulted in the activation of inflammatory processes, as evidenced by the significant increase in the concentration of IL-8 and TNF-α compared to HC animals." (PMID 35132375, 2022). "During the pathogenesis of DSS-induced colitis, we investigated the expression of the proinflammatory cytokines IL-6, IL-1β, and TNF-α, which are abundantly recruited in mice during DSS-induced colitis." (PMID 36187993, 2022). "β-myrcene was also effective in preventing the increase in proinflammatory mediators (COX-2 and iNOS) and cytokines (IL-6, IL-1β and TNF-α) at protein and mRNA expression levels and resulting in colitis remission." (PMID 36557879, 2022). "For comparison, injection of anti-TNFα neutralizing antibodies partially ameliorated colitis with moderately lowered histology score and ODA." (PMID 35840034, 2022). "NF-κB/p65 possesses the role as a “master regulator” of inflammation and aggravates colitis by promoting the expression of inflammatory cytokines (IL-1β, TNF-α, etc.)." (PMID 35126813, 2022). "The mean age of the participants was 41.4 ± 14.7 years; 34 (64.2%) participants were female; 25 (47.2%) had pan-colitis; 22 (41.5%) had left-sided colitis; 16 (30.2%) were on immunosuppressants; and 13 (24.5%) were on anti-TNF medications." (PMID 36014800, 2022). "L-fucose is found to decrease elevated levels of TNF-α, IL-1β, and IL-6 in serum and colonic tissues of mice with a model of colitis." (PMID 36421993, 2022). "Opposite to TNF, there was a reduction in IL-6 levels in the hippocampus of vehicle-treated colitis mice." (PMID 35295931, 2022). "Other studies demonstrated that colitis can increase the amounts of bacteria-derived toxic byproducts (LPS), pro-inflammatory cytokines (including TNF-α, IL-1β and IL-6), and gut leak." (PMID 36275694, 2022). "The TNBS-induced colitis rats showed significant increases in disease activity scores, serum TNF-α, IL-2, and IL-6 levels, and colonic myeloperoxidase and malonaldehyde content." (PMID 35239781, 2022). "In some studies involving the use of experimental colitis animal models, peripheral inflammation elevated the levels of proinflammatory cytokines such as TNF-α, IL-1β, and IL-6 in the hippocampus, cerebral cortex, and hypothalamus." (PMID 36275694, 2022). "In an infection-induced mouse model of colitis, L. rhamnosus ATCC 53103, L. acidophilus ATCC 4356 and L. plantarum A down-regulated the expression of IL-17, TNF-α and IFN-γ, and reduced the colitis-associated histological features." (PMID 35408849, 2022). "Penfluridol effectively inhibited TNFα-induced NF-κB activation in vitro and alleviated the severity of arthritis and colitis in vivo." (PMID 35045889, 2022). "EV were shown to suppress induced p65 translocation in a mice colitis model, effectively reducing the release of proinflammatory cytokines TNF-α, IL-6, and IL-17A, and attenuating clinical symptoms of colitis." (PMID 35335634, 2022). "In the present study, the DSS-induced colitis was ameliorated by the H2S donor NaHS, which was manifested by improved clinical parameters and decreased serum levels of IL-6 and TNF-α." (PMID 36189321, 2022).
colitis (continued). "TNF-α is mainly secreted by macrophages and cell debris, and is a vital player in many inflammatory diseases, liver inflammation, arthritis, and colitis." (PMID 35889786, 2022). "The oral administration of thinned apple polyphenols attenuated gene expression of IFN-γ, TNF-α, IL-1β, IL-6, IL-17, and IL-22 in the colons of mice with colitis." (PMID 35741912, 2022). "Dysfunction of the colonic epithelial barrier can also promote the occurrence and development of colonic inflammation, with pro-inflammatory cytokines such as IL-1β, IL-6 and TNF-α playing a key role in the development of inflammation." (PMID 35514335, 2022). "Cytokines, including IL-2, IL-6, and TNF-α, were measured in blood for cytokine profiling and to identify which cytokines best discriminate experimental colitis from controls." (PMID 35239781, 2022). "Deficiency of those pro-inflammatory cytokines results in reduced colitis and anti-cytokine therapies involving TNF-specific agents composes an important part of clinical therapy in IBD treatment." (PMID 35159480, 2022). "According to the evidence, ATG16L1 deficiency resulted in increased ROS production and impaired mitophagy, which exacerbated colitis in a mouse model through increasing Il-1β expression and TNFα inflammatory factors." (PMID 36499214, 2022). "The acute inflammatory response in DSS-colitis was typified by increased expression of IL-1β, IL-6, and tumour necrosis factor (TNF)-α in the colon." (PMID 36012618, 2022). "In particular, beta-glucans significantly decreased colitis clinical symptoms in mice by the downregulation of pro-inflammatory factor expressions such as IL-1β, TNF-α, and IL-6 in the gut." (PMID 36235770, 2022). "Intestinal epithelial cells' (IEC) specific VDR knockout mice showed more severe colitis and higher expression of TNF-α, IL-1β, and MCP-1 than wild-type mice." (PMID 35600949, 2022). "Conversely, overexpression of HIF-2α in intestinal epithelial cells lead to spontaneous DSS colitis in mice coinciding with an increased expression of TNF, IL-1β and IL-6, whilst deletion of HIF-2α in mice with DSS-induced colitis has a protective effect." (PMID 35769556, 2022). "In the colon tissue or blood from DSS-induced colitis mice, the mRNA and protein levels of pro-inflammatory cytokines (TNF-α, IL-6, and IL-1 β) are enhanced." (PMID 36080669, 2022). "In colitis mice, the mRNA levels of Il-1β (interleukin 1 beta), Ifn-γ (interferon gamma), and Tnf-α (tumor necrosis factor alpha) had increased 3–5 folds in the colon." (PMID 35889745, 2022). "The authors had previously shown in vivo that enhanced brain excitability during colitis requires both elevated cytokines TNF-α and microglial activation." (PMID 34983592, 2022). "We also discovered that DSS activated the signaling pathway NF-κB and increased IL-1β, IL-6, and TNF-α in DSS-induced colitis mice." (PMID 36033869, 2022). "RNVs, SNVs, HSNVs, and LNVs treatment significantly reduced the plasma TNF-α levels that were elevated in DSS-induced mice colitis." (PMID 36077356, 2022). "Exosomes derived from bone marrow DCs treated with IL-10 inhibited the expression of the proinflammatory cytokines IL-2, IFN-γ and TNF-α and trinitrobenzene sulfonate-induced colitis." (PMID 36045437, 2022). "To generate a mouse colitis model dependent solely on human TNF expression, we transferred naive T cells isolated from hTNF-KI donor animals into offspring of hTNF-KI mice crossed with Rag1−/− mice 21,22." (PMID 35383266, 2022). "FMT significantly alleviated DSS-induced colitis and decreased immune cell infiltration in colon tissue, and inflammatory factors expression of IL-1β, TNF-α and IL-17a." (PMID 36578000, 2022). "Polysaccharides isolated from Ganoderma and Lentinula edodes have shown +immunomodulatory activity in colitis animal models through the production of nitric oxide, tumor necrosis factor alpha (TNF-α), and interleukin-6 (IL-6)." (PMID 35576566, 2022).